CRP (C-reactive protein)
Diseases named in the same sentence as CRP in open-access papers (continued):
Sharing a sentence is not in itself a finding about the gene and the disease.
Stroke (continued). "Whereas some studies have focused on CRP levels as a risk factor for future cardiovascular events in RA, studies of CRP levels in patients with SLE in relation to risks of CVD or stroke are scarce." (PMID 34945133, 2021). "Their combination, along with CRP and clinical variables, improved the prediction of infection in stroke patients." (PMID 34092245, 2021). "Previous studies have indicated that elevated CRP levels are correlated with stroke severity and independently predict mortality and the recurrence of stroke." (PMID 34135849, 2021). "C-reactive protein (CRP) is a sensitive marker of inflammation and has been associated with increased risk of coronary heart disease, stroke and vascular mortality in population based studies." (PMID 34117263, 2021). "Serum CRP levels were also significantly greater (p = .043) in stroke patients (1.53 ± 0.38 ng/ml) as compared with those in the control group (1.35 ± 0.35 μg/ml)." (PMID 33210471, 2021). "Female sex, elevated CRP levels, and pre-stroke disability were risk factors for DVT within 7 days of stroke onset, and elevated CRP and pre-stroke disability were independent risk factors for the presence of DVT." (PMID 34488802, 2021). "While circulating CRP is pentameric, local deposition of monomeric CRP has been detected in infarcted myocardial tissue, in brain tissue of stroke patients and in the kidney of diabetic patients with severe chronic kidney disease." (PMID 34707513, 2021). "We investigated the role of CRP, NLR, PLR and MPV on the development of intracranial ISR and recurrent stroke risk." (PMID 34341413, 2021). "In a review, a series of biomarkers, including cytokines, the WBC count, CRP and interleukin 6 (IL-6), were shown to participate specifically in stroke progression." (PMID 34856939, 2021). "A higher baseline C-reactive protein (CRP) is associated with the risk for future cardiovascular events, such as stroke and MI and a reduction of risk appears to be directly related to a reduction in CRP." (PMID 32648087, 2021). "The results confirmed that hs-CRP, ESR, and PLR, which are representative inflammatory markers, show significant positive association with the severity of fatigue in all types of stroke patients and hemorrhagic stroke patients." (PMID 34828631, 2021). "CRP is of clinical importance as an early prognostic factor after stroke because it is an easily measured and clinically common indicator of inflammation." (PMID 34212039, 2021). "Patients with high TMAO concentrations (≥ 2.5 μmol/L) had higher prevalence of CAD, stroke, and peripheral arterial disease, and higher C-reactive protein (CRP) levels and lower eGFRs at the time of ICU admission." (PMID 34674768, 2021). "In another trial, atorvastatin and rosuvastatin revealed lipid-lowering and anti-inflammatory effects in stroke patients and reduced CRP levels, although rosuvastatin showed better therapeutic benefits." (PMID 34489618, 2021). "Exhaled decanal levels steadily increased over the first 7 days after stroke onset, in parallel to blood CRP and IL-6 concentration, suggesting that decanal is likely associated with systemic inflammation." (PMID 34753981, 2021). "This review is aimed at systematically and comprehensively evaluating the evidence regarding the effect of statin on CRP in patients with stroke to provide the groundwork for future studies." (PMID 34489618, 2021). "Our research showed the beneficial impact of statins in patients after a stroke by reducing CRP levels confirming available evidence regarding the potential benefits of statins as anti-inflammatory agents." (PMID 34489618, 2021). "An additional finding of the study was that disability after the stroke was predicted by age and serum CRP." (PMID 31037709, 2021). "As a result, the PCT, CRP, SIL-2R, WBC, dysphagia, time to ambulation, consciousness disorder, and invasive procedure were independent risk factors of pulmonary infection in stroke patients." (PMID 34967381, 2021).
Stroke (continued). "This is supported by pre-clinical evidence in a stroke model in rats and subsequent application of high amounts of human CRP." (PMID 33679775, 2021). "The role of inflammation in stroke recurrence, investigated by traditional biomarkers such as IL-6 and CRP, has been well established." (PMID 34879833, 2021). "In several trials, statin therapy has been shown to significantly reduce the plasma level of CRP and patients with any stroke history who have low CRP levels after statin therapy have better clinical outcomes than those with higher CRP levels." (PMID 34489618, 2021). "Factors associated with the presence of J-waves were old age, female sex, a history of stroke and/or heart failure, high CRP levels as well as a high BMI." (PMID 34648510, 2021). "The percentages of patients who had a CRP level >0.10 mg/dL were 35.4% in the non-stroke group and 44.2% in the stroke group." (PMID 34135849, 2021). "It has been shown that patients with large stroke volume have high WBC count and CRP levels in the acute phase of stroke." (PMID 34090375, 2021). "In the present review, only two studies were designed to directly assess the effects of statins on CRP levels in stroke patients due to their pleiotropic activities." (PMID 34489618, 2021). "CRP levels are elevated in the first 48 hours after onset and remain high for 3-6 months after stroke." (PMID 34212039, 2021). "EuroSCORE, history of atrial fibrillation/atrial flutter, pulmonary disease, previous stroke, CRP, creatinine, hsTNT and NT-proBNP)." (PMID 33653283, 2021). "Elevated CRP levels and pre-stroke disability were also found to be significant factors for the presence of DVT in our patients." (PMID 34488802, 2021). "They concluded tryptophan degradation, which also correlated with CRP, was predictive of acute stroke severity and long-term stroke outcome." (PMID 34753981, 2021). "CRP is probably more informative with respect to acute indolent inflammatory status that very acute changes in stroke." (PMID 34685473, 2021). "Considering mCRP as a significant contributor to the triggering of AD after stroke and to the progression of neuroinflammation and loss of synaptic function in AD, effective treatments against it may be able to decrease poststroke AD cases and other diseases involving CRP activation." (PMID 34356892, 2021). "In general, a clinically useful marker of the advancement of the ongoing inflammatory processes is CRP (C-reactive protein), and in stroke patients the concentration of this marker is significantly elevated." (PMID 34868060, 2021). "The univariate regression analysis showed that an age ≥70 years, a history of stroke, elevated C-reactive protein, and a low albumin level were significantly related to the presence of PLLCT." (PMID 33260480, 2020). "Numerous clinical studies as well as meta-analysis studies have established that CRP was an independent risk factor for cardiovascular disease, including CHD, myocardial infarction, stroke, and other vascular mortality." (PMID 32410858, 2020). "In previous studies in patients with TIA or lacunar stroke CRP levels measured within 24 h or <3 weeks after stroke, respectively, were an independent predictor of further events." (PMID 32733466, 2020). "The C-reactive protein of all patients in this group of cases before stroke was higher than normal value." (PMID 33221756, 2020). "Increased levels of acute-phase reactants, including leukocyte count and serum concentrations of C-reactive protein, D-dimer, ferritin, and lactate dehydrogenase, are the most common predictors of stroke." (PMID 32953353, 2020). "CRP levels measured after stroke correlated with recurrence both in studies limited to cardioembolic stroke or to large-artery occlusive disease and also in studies where patients with ischemic stroke of different etiologies were included." (PMID 32733466, 2020).
Stroke (continued). "Compared with those without PSD, PSD patients showed higher age, ratio of female and widowhood, stroke severity and 3-month functional disability, as well as higher serum levels of Hs-CRP and HCY." (PMID 32040942, 2020). "CRP was found significantly higher in the pneumonia group as compared to the stroke mimic group at BL and at 48 and 120 h and to the stroke without pneumonia group at 48 and 120 h." (PMID 33240188, 2020). "Patients with greater depressive symptoms at day 8 and patients with greater depressive symptoms 3 months after stroke had higher CRP level (median: 7.9 vs 4.3 mg/L, P < 0.01 and 6.7 vs 3.4 mg/L, P = 0.01, respectively)." (PMID 31996746, 2020). "High CRP values have been reported in patients who suffer an ischemic stroke, and are correlated with prognosis, emphasizing the role of inflammation in stroke pathogenesis." (PMID 32512870, 2020). "We prospectively recruited 572 patients with ischemic stroke or transient ischemic attack in whom serum CRP level was measured within 48 h after stroke onset." (PMID 31996746, 2020). "In the first sub-analysis, we excluded patients in whom serum CRP level was measured within 12 h after stroke onset (N = 113)." (PMID 31996746, 2020). "In general, in patients with major strokes, CRP levels correlate with stroke severity and can be a marker of stroke etiology, with higher CRP in more severe cardioembolic or large artery disease stroke than in stroke caused by small artery disease." (PMID 32733466, 2020). "Of 750 patients that participated in the PROPOLIS study, 572 patients had an ischemic stroke or TIA and the CRP measurement within 48 h after stroke onset." (PMID 31996746, 2020). "Compared to the well-established associations of CRP with risk of CHD, observational evidence concerning the relevance of inflammation to individual stroke types is limited." (PMID 32221345, 2020). "In a double-blind randomized clinical trial among stroke patients, fisetin was found to prolong the therapy window of rtPA treatment, likely by reducing levels of MMPs and C-reactive protein (CRP)." (PMID 33383852, 2020). "The largest study tested 14 different biomarkers, including interleukin 6 and CRP, and limited utility in stroke prediction was found." (PMID 32101136, 2020). "CRP levels increase in the first 48 h after onset, are still elevated at 7 days and remain high for 3–6 months after stroke." (PMID 32733466, 2020). "Some important SNP polymorphisms were discovered associated with IS including 5 C-reactive protein (CRP) SNPs, or (rs9943582, -154G/A) in the 5' flanking region of (APLNR) was shown to be significantly associated with stroke in the Japanese population." (PMID 31899762, 2020). "In the second sub-analysis, we included only patients in whom CRP level was measured within 24 h after stroke onset (N = 292)." (PMID 31996746, 2020). "The AIC-based analysis revealed hs-CRP baseline levels together with the presence of a prior stroke and a prior TIA as the best set of potential predictors for bleeding events." (PMID 31984306, 2020). "In another stroke study, patients who died during the study period had significantly higher CRP levels at admission compared to survivors and CRP levels correlated with the clinical outcome after 3 months follow-up." (PMID 32932587, 2020). "Many studies have shown that hs-CRP is significantly higher in patients with ischaemic stroke and positively correlates with the severity of stroke." (PMID 31284487, 2019). "Stroke patients with poor outcome were more likely older, suffered from atrial fibrillation and have high blood levels of glucose and CRP but less likely to receive acute treatment." (PMID 31412946, 2019). "In stroke patients, neural tissue ischemia triggers an acute systemic inflammatory reaction characterized by a significant increase in blood C-reactive protein (CRP) and Interleukin-6 (IL-6)." (PMID 31614478, 2019).
Stroke (continued). "Stroke, elevated CRP, lower BMI level, and younger age at admission are, however, independent risk factor of poor outcomes." (PMID 30670069, 2019). "In our study, a significantly higher NLR was found in stroke patients who had higher hs-CRP (≥3 mg/L)." (PMID 31284487, 2019). "Many studies have discussed the relation between hs-CRP level and the occurrence of atherosclerotic and thrombotic events (MI and stroke) (-)." (PMID 31814936, 2019). "Of note, the level of Hs-CRP was significantly increased in the severe-stroke group vs. the minor-stroke group." (PMID 31164999, 2019). "Patients with atherothrombotic stroke had significantly higher CRP relative to the lacunar or idiopathic strokes." (PMID 31242583, 2019). "The following variables were put into multivariable logistic regression model: age, sex, BMI, stroke syndrome, stroke etiology, vascular risk factors, pre-stroke treatment, lesion volumes, and blood levels of TG, TC, HCY, Hs-CRP and FBG." (PMID 31142624, 2019). "High sensitivity CRP is an inflammatory biomarker for myocardial infarction, stroke and peripheral arterial diseases." (PMID 31501455, 2019). "In-line with our results, CRP elevation within 30 days of stroke also highly predicted long-term survival." (PMID 30718369, 2019). "Our present findings that CRP and FGA levels were associated with the three ischemic stroke subtypes confirm previous findings in other cohorts of stroke patients." (PMID 31242583, 2019). "In stroke patients, CRP was reported as a predictor not only of early mortality but also long-term mortality." (PMID 29954339, 2018). "The concentrations of CRP and its predication values on variety of stroke phenotypes are influenced by the ethnic genome background in the different racial groups, sex, and the environment." (PMID 30254628, 2018). "After adjusting for sex, race-ethnicity, age, CRP, serum folate and cotinine, and congestive heart failure, stroke, and chronic bronchitis, participants with more than 7 components of GCH metrics had a lower risk of poor cognitive functioning." (PMID 29813084, 2018). "Cytokines such as IL-10 or tumor necrosis factor as well as other inflammatory proteins like C-reactive protein (CRP), high-mobility group box-1 or heat shock proteins have been considered as potential biomarker candidates in stroke patients." (PMID 30233311, 2018). "Numerous studies have confirmed that CRP is a predictive marker for cardiovascular disease and that HRT use in postmenopausal women increases the risk of stroke and blood clots." (PMID 29706967, 2018). "The blood level of high sensitive C-reactive protein (hs-CRP) is used as a marker for the risk of complications arising from CVD, like heart attack, strokes, and others." (PMID 30158993, 2018). "The majority of CRP research has focused on the role of CRP and its isoforms on cardiovascular disease and stroke." (PMID 29706967, 2018). "Compared with controls, RIPost was shown to be able to reduce the recurrence of stroke or transient ischaemic attacks, levels of National Institutes of Health Stroke Scale score, modified Rankin Scale score and high-sensitivity C-reactive protein." (PMID 29858664, 2018). "In this study, the anti-inflammatory drug (canakinumab) in 150-mg and 300 mg doses, four times a year, achieved a 40% relative risk reduction (RRR) in plasma CRP and IL-6 levels, in addition to a 15% RRR in the incidence of MI, stroke, or CV death." (PMID 29644229, 2018). "The relationship remained after adjustment for multiple factors including gender, age, history of stroke, history of coronary heart disease, current smoking, current alcohol consumption, physical inactivity, education attainment, CRP, serum uric acid, and BMI." (PMID 29372543, 2018). "Here, stroke sequelae (HR 2.25,95%CI 1.09-4.67) and CRP (HR 1.02[per mg/L], 95%CI 1.01-1.03) also were found to besignificantly associated with increased mortality risk." (PMID 28443959, 2017).
Stroke (continued). "Statistical evaluation revealed an independently positive correlation between lesion volume and CRP, IL-6, and IL-23 on day 3 after stroke onset (all p < 0.05)." (PMID 27682880, 2017). "We selected participants who had a confirmed diagnosis of stroke by a registered physician, who had been utilising rehabilitation services for at least 1 month at CRP and who had agreed to participate in this study." (PMID 29078803, 2017). "Age, baseline CRP levels and stroke sequelae were confirmed as independent riskfactors for death during the 5-year follow-up period." (PMID 28443959, 2017). "CI-AKI risk score = 0.2232*DM + 0.2188* acute MI + 0.013*years since drinking + 0.0025*SBP – 0.4489*sex – 0.0001*LDH – 0.0011* Hs-CRP – 0.725*CKD – 0.0013* stage of CKD – 0.1994*stroke – 2.0130." (PMID 29088847, 2017). "Here, we showed that IFN-γ was negatively correlated with lesion volume on day 3 after stroke, but that CRP, IL-6, and IL-23 were positively correlated with lesion volume at that time point." (PMID 27682880, 2017). "Studies employing the ultrasensitive latex-enhanced immunoassay (Latex) for high-sensitivity CRP (hs-CRP) concentration analysis have reported that hs-CRP is useful in the prediction of myocardial infarction and stroke." (PMID 28467440, 2017). "The aim of this study was to provide an overall view of stroke patients who took-up rehabilitation services at CRP." (PMID 29078803, 2017). "In this study, we provided a snapshot demographic view of patients attending CRP for stroke rehabilitation." (PMID 29078803, 2017). "The systolic blood pressure, diastolic blood pressure, TC, LDL-C, fasting plasma glucose, and Hs-CRP were significantly higher in stroke patients than in healthy subjects." (PMID 29228037, 2017). "In our study, the serum levels of TNF-α, CRP, IL-4, and IL-10 were all significantly increased in stroke patients, whereas, the serum level of IFN-γ was decreased compared with that in control subjects." (PMID 27682880, 2017). "CRP levels were higher in the presence of stroke than in the absence [6.5 (5.0–12.0) vs. 6.3 (4.1–12.0); p = 0.029]." (PMID 28854899, 2017). "We also report the appropriate cutoff of CRP for adverse consequences of stroke including poor outcome and mortality." (PMID 27757207, 2016). "Correlation analyses were then performed to investigate the association of CRP, homocysteine and Klotho biomarkers with the occurrence of previous vascular events (CAD, MI and stroke) at baseline." (PMID 28076518, 2016). "Previous studies showed that C-reactive protein (CRP), an inflammatory marker, was associated with stroke severity and long-term outcome." (PMID 27355961, 2016). "When hs-CRP levels were compared in different subtypes of stroke, the mean hs-CRP level was more in HS than ischemic stroke." (PMID 27648176, 2016). "The highly sensitive C-reactive protein (hsCRP), an established marker of inflammation, has been demonstrated to be a predictor of myocardial infarction, stroke, peripheral arterial disease and sudden cardiac death." (PMID 27195017, 2016). "In stroke patients, higher CRP levels in the blood were also shown to be an independent risk factor of future vascular events or mortality." (PMID 27258004, 2016). "This is comparable to ranges described in an earlier study, which reported CRP values of 4 mg/L on admission and a peak of 18 mg/L at 5–7 days after stroke." (PMID 26937636, 2016). "In patients with acute stroke, some studies showed that CRP was related to post-stroke functional outcome, whereas other groups reported that the association disappeared after adjusting for confounders." (PMID 27258004, 2016). "Nevertheless, patients with severe stroke are likely to be hospitalized early, when CRP levels are still on the rise." (PMID 27258004, 2016). "In this study, a mean value of inflammatory marker hs-CRP in total stroke patients was higher as compared to control groups." (PMID 27648176, 2016).